CDH23 (cadherin related 23)
Diseases named in the same sentence as CDH23 in open-access papers (continued):
Sharing a sentence is not in itself a finding about the gene and the disease.
cutaneous melanoma (1 paper, 2020). A primary melanoma arising from atypical melanocytes in the skin. "In this study, we observed that cutaneous melanoma samples had a lower CDH23 expression when compared to normal skin samples and this low expression was significantly correlated with a worse overall and disease-free survival." (PMID 32276436, 2020). "We then investigated each gene’s expression and its prognostic value in melanoma, revealing significant CDH23 downregulation in cutaneous melanoma (SKCM) samples, when compared with normal skin samples." (PMID 32276436, 2020). "In summary, we have identified three novel mutations in CDH23, ARHGEF40, and BRD9 genes, which could confer cutaneous melanoma susceptibility." (PMID 32276436, 2020).
ductal adenocarcinomas (1 paper, 2018). "Transcripts significantly overexpressed in ductal adenocarcinomas include CD24, CDH23 (cadherin-like 23), and PRLR (prolactin receptor)." (PMID 29581876, 2018).
esophageal cancer (1 paper, 2019). A primary or metastatic malignant neoplasm involving the esophagus. "Our immunohistochemical studies with TMA slides of lung and esophageal cancer also corroborated the TCGA mRNA expression with the Cdh23‐protein expression." (PMID 30747484, 2019).
gastric cancer (1 paper, 2020). A primary or metastatic malignant neoplasm involving the stomach. "Overall, this data supports the hypothesis for the pathogenicity of this rare CDH23 variant, as it could play a similar role to that of CDH1 in gastric cancer." (PMID 32276436, 2020).
hereditary retinal degeneration (1 paper, 2025). "Cadherin-23 (CDH23) is a non-classical cadherin protein that belongs to the cadherin superfamily, which has been identified as a genetic cause of hereditary retinal degeneration, i.e., the retinal cadherinopathies." (PMID 40429749, 2025).
Hyporeflexia (1 paper, 2024). Reduction of neurologic reflexes such as the knee-jerk reaction. "Among the patients with CDH23 variants, three out of 11 (27%) had semicircular canal dysfunction (one bilateral hyporeflexia and two unilateral hyporeflexia)." (PMID 38720048, 2024).
inner ear disease (1 paper, 2024). "For example, a new mouse mutant of the CDH23 gene with early-onset hearing loss has emerged to facilitate the evaluation of otoprotection drugs on some form of inner ear disease linked to mutations in the CDH23 gene such as ARHL." (PMID 38333758, 2024).
Insulin resistance (1 paper, 2019). Increased resistance towards insulin, that is, diminished effectiveness of insulin in reducing blood glucose levels. "Cadherin 3, type 1, P-cadherin (CDH3), CDH2, PCDH20, and CDH23 are novel biomarkers for the development of insulin resistance." (PMID 30678306, 2019).
KBG syndrome (1 paper, 2025). KBG syndrome is a rare condition characterized by a typical facial dysmorphism, macrodontia of the upper central incisors, skeletal (mainly costovertebral) anomalies and developmental delay. "Although the patient’s clinical presentation supports an expansion of the KBG syndrome phenotype, causal conclusions are precluded by the coexistence of additional genetic variants, including a 3p26 duplication and CDH23 mutations." (PMID 40760574, 2025).
melanoma (1 paper, 2020). A malignant, usually aggressive tumor composed of atypical, neoplastic melanocytes. "Altogether, these results suggested that CDH23, ARHGEF40, and BRD9 genes could be also important for sporadic melanoma and consequently, a mutation in these genes could be pivotal in this disease." (PMID 32276436, 2020). "Since CDH23, ARHGEF40, and BRD9 function is unclear, the impact of rare variants in these genes in melanoma context is unknown." (PMID 32276436, 2020). "Besides, as CDH23 seems to regulate ERK and MAPK cascades, known melanoma-signalling pathways, mutations in this gene might play a role in MPM development by modulating the activity of these molecules." (PMID 32276436, 2020).
Obesity (1 paper, 2019). Accumulation of substantial excess body fat. "Specifically, previous studies have found that SNPs within Cdh23 were correlated with BMI, SNPs in Tph2 were correlated with obesity, SNPs in Prox1 were correlated with glucose metabolism, SNPs in Lipc were correlated with cholesterol, and SNPs in Pnpla3 were correlated with hepatic lipid content." (PMID 31262088, 2019).
osteoarthritis (1 paper, 2022). A noninflammatory degenerative joint disease occurring chiefly in older persons, characterized by degeneration of the articular cartilage, hypertrophy of bone at the margins and changes in the synovial membrane. "Genes annotated to these methylation sites are linked to osteoarthritis-relevant terms in cartilage, e.g., they encode a matrix metalloproteinase (MMEL1) or are involved in cell adhesion (CDH23 and PARVA)." (PMID 35679866, 2022).
tooth agenesis (1 paper, 2017). A tooth disease characterized by failure to develop one or more missing teeth. "In summary, we found that novel variants in previously reported causal genes appear to mainly contribute to tooth agenesis of the anterior region, and the research using exome sequencing suggested the association between FAM65A, NFATC3 and CDH23 or SMIA." (PMID 28265457, 2017).
vitiligo (1 paper, 2022). Generalized well circumscribed patches of leukoderma that are generally distributed over symmetric body locations and is due to autoimmune destruction of melanocytes. "The results of a vitiligo GWAS in the Han Chinese population identified rs10876864-PMEL, rs638893-CXCR5/DDX6, and rs11417210-SLC29A3/CDH23 to be associated with vitiligo risk." (PMID 36008553, 2022).
cancer (14 papers, 2016 to 2025). A tumor composed of atypical neoplastic, often pleomorphic cells that invade other tissues. "In fact, CDH23 has been shown to be associated with a positive inflammatory response, which plays a pivotal role in cancer." (PMID 32276436, 2020). "Although the role of CDH23 in cancer progression and prognosis has been illustrated earlier, systematic and comprehensive analysis of its role in AML using bioinformatics tools has not yet been conducted." (PMID 35597916, 2022). "It was reported that CDH23 was downregulated via DNA methylation in various tumors, and suppressed cancer cell migration and promoted aggregation of cancer cells." (PMID 34252883, 2021). "Further, we observed increased methylation for both LUAD and ESCC with higher lymph node status (N1–2) than no lymph node involvement (N0), reinforcing the strong correlation of cancer metastasis with the down‐regulation of Cdh23 mRNA." (PMID 30747484, 2019). "Next, we experimentally verified the function of intrinsic Cdh23 in cancer cell‐lines differentially expressing Cdh23." (PMID 30747484, 2019). "From our experimental observations with TCGA and THPA we propose an essential role of Cdh23‐mediated strong cell–cell adhesion, which is significantly regulated in cancer." (PMID 30747484, 2019). "The Cancer Genome Atlas (TCGA) marks the significant down‐regulation of Cdh23‐mRNA in 24 types (65%) of cancers among 37 types and up‐regulation in four types." (PMID 30747484, 2019). "Our data from experiments and data‐mining indicate that Cdh23 can potentially inhibit the spread of cancer to lymph nodes and metastasis." (PMID 30747484, 2019). "Overall, in silico analysis and TMA analysis suggest that Cdh23 is decreased in cancer, which is further decreased in advance lymph node stages and metastatic stages, suggesting Cdh23 suppresses cancer cell metastasis." (PMID 30747484, 2019). "Since the disintegration of cell–cell adhesion from primary tissues and acceleration in cell migration are significant steps in metastatic dissemination, we traced the relation between Cdh23 expression and cancer metastasis." (PMID 30747484, 2019). "Here, we performed immunofluorescence studies that revealed that Cdh23 is present as distinct puncta at the cell–cell boundaries of cancer cells." (PMID 30747484, 2019). "Overall, in vitro analysis of cancer cell lines suggests that Cdh23 can suppress cancer cell migration and promote aggregation." (PMID 30747484, 2019). "The cell migration rate in cancer cells is further accelerated by the presence of excretory isoforms of Cdh23, which loosen its cell‐adhesion ability by competitive binding." (PMID 30747484, 2019). "Next, to locate Cdh23 in cells with intrinsic expression of this cadherin, we performed a quantitative qRT‐PCR‐based sorting of cancer cells by Cdh23‐mRNA expression (Cdh23 IS1 primers)." (PMID 30747484, 2019). "Among the three selected cancer cells lines, we quantified from mRNA expression that both Cdh23 and Ecdh are uniformly expressed in A549." (PMID 30747484, 2019). "Immunofluorescent staining of intrinsic expression of Cdh23 showed puncta at the homotypic cell–cell junctions of A549 cancer cells." (PMID 30747484, 2019). "For example, re-expression of CNTN1, ITGA5, and CDH23 increased the numbers of colonies in the enhancer KO cells, affecting important properties of cancer cell growth." (PMID 31328168, 2019). "Using HEK293T cells and four types of cancer cells differentially expressing Cdh23, we observed that cell migration was faster in cells with reduced levels of Cdh23 expression." (PMID 30747484, 2019). "We observed less expression of Cdh23 protein in cancer‐adjacent TMA and cancer TMA than normal, and a further decrease in protein expression for metastatic lymph node TMA." (PMID 30747484, 2019). "The next aim was to understand the functional role of Cdh23 in normal tissues and what cancer cells gain or lose in regulating the protein." (PMID 30747484, 2019).
cancer (continued). "We identified a uniform expression of Cdh23 at the cell–cell boundaries in different normal and cancer tissues." (PMID 30747484, 2019). "In the present study, the smoking-related methylation changes to RUNX3, IL6R, PTAFR, and ANKRD11 (cardiovascular-related genes) and CEP135 and CDH23 (cancer-related genes) corresponded to increased gene expression." (PMID 26756918, 2016). "CDH23 upregulated the viability of cancer cells in suspension culture, and this action may involve AKT pathway activation." (PMID 39744166, 2025). "The enrichment functions of CDH23 show that CDH23 takes part in the essential biological functions, including cancer cell growth, cell metastasis, cell adhesion, cell cycle, drug catabolic process, leukocyte mediated immunity, DNA replication, DNA repair, and so on." (PMID 34252883, 2021). "CDH23 can suppress cancer cell migration and promote aggregation in vitro." (PMID 34252883, 2021). "Moreover, silencing of both Ecdh and Cdh23 resulted in increased cell migration and significant cell disaggregation, suggesting both can have a synergistic effect on cancer cell migration." (PMID 30747484, 2019). "Faster migration in the presence of free Cdh23 EC1–2 (mimicking the soluble isoforms) proteins suggests that the cancer cells can facilitate migration by decreasing Cdh23 IS1 expression by promoter methylation and by the expression of soluble isoforms that interfere with homodimer formation." (PMID 30747484, 2019). "We hypothesized that the down‐regulation of Cdh23 during tumorigenesis weakens the cell–cell junction and promotes cancer cell migration leading to metastasis." (PMID 30747484, 2019). "Based on this hypothesis, here we first established the widespread expression of Cdh23 in different normal and cancer tissues using in silico and experimental approaches, and deciphered its down‐regulation in cancer." (PMID 30747484, 2019). "Therefore, CDH23 may play a critical function in cancer progression; however, its specific role and mechanism of action are unclear." (PMID 39744166, 2025). "Functional enrichment analysis showed that CDH23 mainly enriched in cancer cell growth, cell metastasis, cell adhesion, cell cycle, drug catabolic process, leukocyte mediated immunity and DNA repair by some cancer related kinases, miRNAs and transcription factors." (PMID 34252883, 2021). "Epigenetic alteration of CDH23 may play important roles in cancer progression." (PMID 34252883, 2021). "Similarly, in ESTA, metastatic SCC (84.2%) has a higher percentage of tissues with low‐Cdh23 expression compared with the SCC (72.6%) and normal esophageal mucosa adjacent to cancer (50%), further strengthening our observation of a decrease in Cdh23 expression during ESTA progression." (PMID 30747484, 2019). "To check, we monitored the cell-aggregation among cancer cell lines, HEK293, HeLa, HaCaT, and A549 that express endogenous Cdh23 differentially." (PMID 36934176, 2023). "Cadherin-23 (CDH23) plays an important role in intercellular adhesion and is involved in the progression of several types of cancer." (PMID 35597916, 2022). "Cadherin-23(CDH23) mediates homotypic and heterotypic cell-cell adhesions in cancer cells." (PMID 34252883, 2021).
tumor (14 papers, 2012 to 2025). "Case studies with tumor patients suggested that the expression level of CDH23 associated with patient survival and metastasis." (PMID 34252883, 2021). "The results of multivariate analysis showed that CDH23 expression and residual tumor were adverse factors for overall survival." (PMID 39744166, 2025). "Relationship of CDH23 with immune infiltration level was determined using Tumor Immune Estimation Resource (TIMER)." (PMID 35597916, 2022). "In conclusion, CDH23 had an extensive influence on the regulation of several pathways and processes involved in tumor immunity." (PMID 35597916, 2022). "We also comprehensively analyzed the functional pathways of CDH23, which provided bioinformatics and computational biology-based insights for further understanding of the role played by CDH23 in tumor processes." (PMID 35597916, 2022). "In this study, we investigated the expression profile and biological functions of CDH23 in AML and further analyzed the association between CDH23 expression and the AML tumor immune microenvironment using systematic bioinformatics analysis." (PMID 35597916, 2022). "A 327 bp homozygous deletion (scaffold_12:20762508-20762835), which overlaps CDH23 gene, was uncovered in tumor cell line when HCC1395BL_v1.0 was used as reference, which includes a copy of SINE/AluY (284 bp), but this AluY sequence is not present in GRCh38." (PMID 36352452, 2022). "We also investigated the potential correlation between CDH23 expression and tumor immune infiltration in AML." (PMID 35597916, 2022). "Collectively, these results suggested that the expression level of CDH23 was highly correlated with tumor immune infiltration and the TME." (PMID 35597916, 2022). "The results showed that CDH23 had a negatively significant correlation with tumor purity (cor=-0.307, p=4.8e-02)." (PMID 34252883, 2021). "The relationship analysis between CDH23 expression and immune cell infiltration showed that CDH23 had a negatively significant correlation with tumor purity." (PMID 34252883, 2021). "The relationship between CDH23 and the immune cell infiltration was explored by the Tumor Immune Estimation Resource (TIMER)." (PMID 34252883, 2021). "The deletion of the rs55958994-associated enhancer leads to the down-regulation of ITGA5, CDH23, and CNTN1, to defects of tumor initiation, growth, and invasive migration, and to a decrease in the percentage of CSCs." (PMID 31328168, 2019). "In the tumor of patient #1, we detected mutations in tumor suppressor genes such as MYO18B and CTNN2 and in genes related to adhesion, invasiveness, and survival (e.g., CDH23, HMCN1, and OBSCN) in samples collected at the resistance that were not present initially." (PMID 37620318, 2023). "In brief, these findings suggest that CDH23 may be involved in tumor processes including tumor invasion, phagocytosis, granulocyte activation, and neutrophil-mediated immunity." (PMID 35597916, 2022). "In addition, functional enrichment analysis established that CDH23 plays a crucial role in tumor immunity." (PMID 35597916, 2022). "CDH23 may be involved in mediating tumor immune environment, and this highlights the potential of CDH23 as a therapeutic target in AML." (PMID 35597916, 2022). "Finally, we performed SMFS with Cdh23 EC1‐2 (WT) to estimate the strength of the interfaces as in cellulo studies measured strong adhesive properties of Cdh23 that suppresses tumor metastasis." (PMID 31729176, 2019). "Eight genes (CDH23, HARS2, LLGL2, LTBP1, MAP6D1, MIPOL1, SCYL3, ZNF418) showed some degree of promoter methylation in at least one tumour, but only MIPOL1 exhibited probable homozygous methylation in more than one sample." (PMID 39794353, 2025). "Additionally, the expression of CDH23 may mediate immune infiltration of tumor." (PMID 35597916, 2022).
tumor (continued). "The results of univariate analysis showed that better 5-year overall survival of patients was correlated with low CDH23 expression, early tumor stage, no residual tumor, early histological grade and negative vascular invasion (P < 0.05)." (PMID 39744166, 2025). "In addition, the organoids recapitulated the genetic alterations of the patient’s primary tumor (e.g., single nucleotide variations in BMP4, cadherin related 23 (CDH23), AKT serine/threonine kinase 1 (AKT1)), as uncovered by whole-exome sequencing." (PMID 37614709, 2023). "To verify how methylation can control the Cdh23‐expression, we compared the methylation sites in various regions of Cdh23 gene (Promoter, CpG island, 5′UTR, gene body, 3′‐UTR) for normal (n = 32) and LUAD tumor (n = 463) patients as deposited in MethHC database in TCGA." (PMID 30747484, 2019).
genetic disorders (3 papers, 2024 to 2025). "CDH23 (cadherin-related 23) is a gene that is associated with various genetic disorders affecting hearing and vision." (PMID 39596651, 2024).
infection (1 paper, 2018). The state of being infected such as from the introduction of a foreign agent such as serum, vaccine, antigenic substance or organism. "First, we observed that the real-time qPCR amplification using primers D (located at the 3′ end of vector 2) and E (located at the 5′ of vector 3) following infection with AAV 2 + 3 is significantly lower than the one obtained when AAV 1 + 2 + 3 are used (2% for CDH23 and 20% for ALMS1)." (PMID 29292161, 2018).
neurological disorders (1 paper, 2019). "Additionally, genes previously associated with neurological disorders were similarly up regulated, such as Mdga2, Clu, Epha3, Chl1, Cntn4, Cdh23, and Pard3b." (PMID 30628890, 2019).
retinopathies (1 paper, 2022). "It remains unclear whether these genetic findings are related to the pathology in this family, since the proband had no retinopathies or vestibular abnormalities, as seen in Usher Type D syndromes associated with mutations in CDH23 (OMIM #601067)." (PMID 34997062, 2022).
CDH23 also shares sentences with these, for which no sentence is quoted: Hearing impairment (13 papers); CHARGE syndrome (3); psychiatric disorder (3); autosomal recessive hearing loss (2); bipolar disorder (2); ciliopathy (2); cone-rod dystrophy (2); lung adenocarcinoma (2); Usher syndrome type 1B (2); Wolfram syndrome (2); age (1); autism spectrum disorder (1); autosomal recessive retinitis pigmentosa (1); Bardet-Biedl syndrome (1); Bartter syndrome type 4 (1); brain tumors (1); cardiovascular disease (1); cataract (1); coloboma (1); Crouzon syndrome (1); diabetes (1); DiGeorge syndrome (1); dominant optic atrophy (1); DOORS syndrome (1); endocrine tumors (1); Fanconi anemia (1); hearing disorder (1); hereditary sensory and autonomic neuropathy (1); holoprosencephaly (1); hyperthyroidism (1).
A further 21 diseases each share a sentence with CDH23 in 1 paper.